DIP2A (DIP2 acetate--CoA ligase A)
Description:
Catalyzes the de novo synthesis of acetyl-CoA in vitro (By similarity). Promotes acetylation of CTTN, possibly by providing the acetyl donor, ensuring correct dendritic spine morphology and synaptic transmission (By similarity). Binds to follistatin-related protein FSTL1 and may act as a cell surface receptor for FSTL1, contributing to AKT activation and subsequent FSTL1-induced survival and function of endothelial cells and cardiac myocytes.
Synonyms: C21orf106; DIP2; KIAA0184
Tractability: Antibody: UniProt places it where antibodies can reach, with high confidence; its Gene Ontology location is reachable by antibodies, with medium confidence. PROTAC: ubiquitination databases record sites on it; its protein half-life has been measured.
Gene: Protein-coding gene on chromosome 21 (46,458,877 to 46,572,743, forward strand). Ensembl gene ENSG00000160305.
Subcellular location: Cell membrane; Mitochondrion; Cell projection, dendritic spine
Subcellular location (Human Protein Atlas): Nucleoplasm; Actin filaments; Focal adhesion sites; Mitochondria; Plasma membrane
Gene Ontology:
Molecular function: protein binding; acetate-CoA ligase activity
Biological process: negative regulation of gene expression; acetyl-CoA biosynthetic process; dendritic spine morphogenesis; positive regulation of peptidyl-lysine acetylation
Cellular component: cell surface; membrane; plasma membrane; dendritic spine; mitochondrion
Genetic constraint (gnomAD): Loss-of-function variants: 78 observed, 152.57 expected, observed/expected ratio (o/e) 0.51, 90% interval 0.43 to 0.62. The upper end of that interval is the gene's LOEUF score, 0.62, which puts it in group 2 of 6, group 1 being the genes least tolerant of losing a copy. Missense variants: 1,753 observed, 2,026.7 expected, observed/expected ratio (o/e) 0.86, 90% interval 0.83 to 0.9. Synonymous variants: 872 observed, 851.96 expected, observed/expected ratio (o/e) 1.02, 90% interval 0.97 to 1.08.
Homologues: Orthologues: chimpanzee DIP2A (99% identical), macaque DIP2A (97% identical), dog DIP2A (94% identical), mouse Dip2a (93% identical), rat Dip2a (93% identical), guinea pig DIP2A (91% identical), pig DIP2A (90% identical), rabbit DIP2A (86% identical), tropical clawed frog dip2a (85% identical), zebrafish dip2a (83% identical), Drosophila melanogaster DIP2 (58% identical), Caenorhabditis elegans dip-2 (48% identical). Paralogues in human: DIP2C (74% identical), DIP2B (72% identical).
Diseases named in the same sentence as DIP2A in open-access papers:
DIP2A is named in the same sentence as 21 diseases in open-access papers, as found by Europe PMC text mining. Sharing a sentence is not in itself a finding about the gene and the disease. The quoted sentences say what the papers report.
autism (5 papers, 2019 to 2023). Persistent deficits in social interaction and communication and interaction as well as a markedly restricted repertoire of activity and interest as well as repetitive patterns of behavior. "Dip2a‐deficient mice exhibit abnormal spine morphogenesis, reduced synaptic transmission, and autism‐like behavior." (PMID 35611833, 2022). "Deletion of Dip2a in mice is associated with behavioral abnormalities and decreased synaptic glutamate receptor levels, which have been implicated in autism." (PMID 31600191, 2019). "Among these genes, the association of DIP2A and ASD risks has been validated by our team; moreover, Dip2a knockout mice exhibit autism-like behaviors, including excessive repetitive behavior and social novelty defects." (PMID 36750796, 2023). "DIP2A knockout mice exhibited autism-like behaviors, including excessive repetitive behaviors and defects in social novelty." (PMID 34394017, 2021). "Autism candidate gene disconnected-interacting protein homolog 2 A (DIP2A) is known to be involved in acetylated coenzyme A (Ac-CoA) synthesis and is primarily expressed in the brain regions with abundant pyramidal neurons." (PMID 31600191, 2019). "In the present study, we show that DIP2A, coded by the autism candidate gene DIP2A, interacts with cortactin, which is essential for DIP2A-mediated acetylation of cortactin." (PMID 31600191, 2019). "Dip2A knockout blocks acetylation of cortactin and leads to an autism-like phenotype." (PMID 33153107, 2020). "Furthermore, Dip2a knockout (KO) mice exhibited autism-like behaviors, including excessive repetitive behaviors and defects in social novelty." (PMID 31600191, 2019). "The autism candidate gene DIP2A is known to be involved in the synthesis of acetylated coenzyme A, but its precise role in the brain remains largely unknown." (PMID 31600191, 2019). "Besides, Dip2a gene is a candidate for developmental dyslexia and autism." (PMID 33153107, 2020).
Anxiety (3 papers, 2019 to 2024). Intense feelings of nervousness, tension, or panic often arise in response to interpersonal stresses. "Overall, Dip2a KO mice exhibited typical autistic-like behaviors, including increased repetitive behavior and anxiety, and impaired social novelty and communication." (PMID 31600191, 2019). "Similarly, the Dip2A KO shows lower social exploration time of a conspecific, increased self-grooming in both novel and home cage environments, decreased social novelty and increased marble burying indicative of higher anxiety as well as social recognition and interaction deficits." (PMID 35782388, 2022).
Alzheimer disease (2 papers, 2018 to 2022). A progressive, neurodegenerative disease characterized by loss of function and death of nerve cells in several areas of the brain leading to loss of cognitive function such as memory and language. "DIP2A regulates both the synapse formation and the axonal path, and its expression was related to the burden of another neurodegenerative disorder, i.e. the Alzheimer’s disease." (PMID 30463275, 2018).
dyslexia (2 papers, 2010 to 2019). A learning disorder characterized by an impairment in processing written words. "Terminal micro-deletions in this chromosomal region or de novo mutation of DIP2A is associated with developmental delay, substantial susceptibility to autism spectrum disorder (ASD), and dyslexia." (PMID 31600191, 2019). "DIP2A has been reported to be a candidate gene for ASD and dyslexia; we explored whether Dip2a deletion in mice leads to defects in neurodevelopmental disorders." (PMID 31600191, 2019). "The recent identification of S100B as a novel dyslexia candidate gene along with three other genes (i.e., PCNT, DIP2A, and PRMT2) mapping to chromosome region 21q22.3 suggests that decreases in S100B expression might contribute to certain dyslexia phenotypes." (PMID 20827421, 2010).
glioblastoma (2 papers, 2019 to 2025). The most malignant astrocytic tumor (WHO grade IV). "The Fstl1/DIP2A/MGMT pathway is linked to temozolomide resistance in glioblastoma, with increased Fstl1 expression contributing to resistance, while decreased expression enhances drug sensitivity." (PMID 40781854, 2025). "Fstl1, a glycoprotein highly expressed in glioblastoma, competitively binds DIP2A to block DIP2A nuclear translocation, so as to hinder DIP2A from binding the HDAC2–DMAP1 complex." (PMID 30542120, 2019).
amyloid (1 paper, 2022). "Similarly, the function of DIP2A is still unclear, but it was the strongest loading gene in our FDG-18-related analysis and has been associated with amyloid burden in epigenome-wide association (EWAS) studies of AD using post-mortem brain tissue." (PMID 35774552, 2022).
autism spectrum disorder (1 paper, 2019). A spectrum of developmental disorders that includes autism, and Asperger syndrome. "This study shows that loss of DIP2A in mice results in an imbalance in the acetylation of the synaptic protein cortactin, causing defects in spine morphogenesis and synaptic transmission that may establish a link to autism spectrum disorders." (PMID 31600191, 2019). "Altogether, our findings establish an initial link between DIP2A gene variations in autism spectrum disorder (ASD) and highlight the contribution of synaptic protein acetylation to synaptic processing." (PMID 31600191, 2019).
cardiac ischemia (1 paper, 2015). "Protective effect against apoptosis in cardiac ischemia was mediated by activation of DIP2A." (PMID 26605542, 2015).
chronic kidney disease (1 paper, 2021). Impairment of the renal function secondary to chronic kidney damage persisting for three or more months. "We extended our studies of Fstl1 and its receptors Tlr4 and Dip2a in another experimental model of chronic kidney disease: murine UUO." (PMID 34502419, 2021).
glioma (1 paper, 2019). A benign or malignant brain and spinal cord tumor that arises from glial cells (astrocytes, oligodendrocytes, ependymal cells). "Our studies detected five proteins that interacted with Fstl1 in glioma using Co-IP and pulldown experiments, i.e., DIP2A, CD14, BMP4, ActR-IIB, and follistatin, and the mRNA levels of MGMT were only increased in GBM cells transfected with DIP2A-specific siRNA (siDIP2A)." (PMID 30542120, 2019).
steatosis (1 paper, 2023). Increased lipid within the cytoplasm of cells. "FSTL1 could not restore cellular lipid accumulation and lipid metabolism gene expression in Dip2a or Cd14 knockdown AML12 steatosis cells co-cultured with GAS from F4MKO mice." (PMID 37770480, 2023).
cancer (2 papers, 2025 to 2026). A tumor composed of atypical neoplastic, often pleomorphic cells that invade other tissues. "By contrast, in cancer-related studies, the relationship between DIP2A expression and function is more complicated." (PMID 41602834, 2026). "On the other hand, the increased candidates included proteins involved in the blockade of cancer cell migration and invasion (SCAI, CARMIL2), autophagy activation (HSBP1, RILP) as well as proteins that can be considered as anti-tumorigenic (SCG2, DIP2A, HSBP1)." (PMID 39833546, 2025).
tumor (2 papers, 2022 to 2024). "Overexpression of DIP2A has been reported to elevate follistatin‐like 1 (FSLT1) expression in mouse tumour model, inducing immuno‐resistance consequently." (PMID 38279874, 2024). "The expression of DIP2A (the receptor of FSTL1) in tumor cells is the key to FSTL1-induced immune resistance." (PMID 35805015, 2022).
brain diseases (1 paper, 2022). "In addition, DIP2A was associated with abnormal brain development and brain diseases, and SH2D2A was important for proper activation of T-cells." (PMID 35865544, 2022).
neurodevelopmental disorder (1 paper, 2019). A behavioral and cognitive disorder with onset during the developmental period that involves impaired or aberrant development of intellectual, motor, or social functions. "Genetic studies in humans have implicated an association of mutations in the DIP2A gene with neurodevelopmental disorders." (PMID 31600191, 2019).
DIP2A also shares sentences with these, for which no sentence is quoted: developmental delay (2 papers); Intellectual disability (2); autoimmune hepatitis (1); Hydroureter (1); psychiatric disorder (1); vitiligo (1).